Y_RNA (Y RNA )
Gene: Miscellaneous RNA gene on chromosome 7 (6,212,638 to 6,212,740, reverse strand). Ensembl gene ENSG00000202273.
Homologues: Orthologues: chimpanzee Y_RNA (93% identical), macaque Y_RNA (85% identical). Paralogues in human: RNY1 (92% identical), Y_RNA (90% identical), Y_RNA (88% identical), Y_RNA (87% identical), Y_RNA (86% identical), RNY1P11 (85% identical), Y_RNA (85% identical), Y_RNA (84% identical), RNY1P7 (83% identical), RNY1P8 (83% identical), Y_RNA (83% identical), RNY1P12 (83% identical), and 94 more.